CTLA4 (cytotoxic T-lymphocyte associated protein 4)
Diseases named in the same sentence as CTLA4 in open-access papers (continued):
Sharing a sentence is not in itself a finding about the gene and the disease.
psoriasis (44 papers, 2012 to 2026). An autoimmune condition characterized by red, well-delineated plaques with silvery scales that are usually on the extensor surfaces and scalp. "Patient 3 only showed polymorphisms in a region downstream of CTLA4, which have been previously associated to paradoxical psoriasis to anti-TNF-α." (PMID 38495872, 2024). "Treatment with both PD-1/PD-L1 and CTLA-4 inhibitors entails a risk for the development of psoriasis or exacerbation of a pre-existing psoriatic disease." (PMID 37370736, 2023). "CTLA4 encodes a protein that inhibits T cells and has an inverse correlation with psoriasis severity, as psoriasis is characterized by increased T-cell infiltration." (PMID 37569685, 2023). "Moreover, blocking CTLA-4 function in a mouse model of psoriasis induced by imiquimod was associated with increased epidermal thickness and high amounts of CD3+ T cells." (PMID 38399624, 2024). "Thus, our results suggest that the mechanisms underlying the actions of CTLA-4-Ig and the dNP2-ctCTLA-4 peptide are fundamentally different which provides a plausible explanation for the divergent outcomes observed in the psoriasis experiments." (PMID 37818377, 2023). "A CTLA-4–mimetic peptide (dNP2-ctCTLA-4) has also improved the Treg/effector balance and alleviated inflammation in psoriasis." (PMID 40933988, 2025). "Certain SNPs in genes like IL23R, FBXL19, CTLA4, SLC12A8, TAP1, and others predispose individuals to paradoxical psoriasis." (PMID 39000125, 2024). "CTLA4 is a co-inhibitory molecule that acts by limiting T helper cell hyperactivation, and CTLA4 expression has been found to be inversely correlated with psoriasis severity." (PMID 38303723, 2024). "To investigate the impact of dNP2-ctCTLA-4 peptide and CTLA-4-Ig on lymphoid cells in psoriasis-like skin inflammation, we conducted a flow cytometry analysis." (PMID 37818377, 2023). "In this study, we investigated the effects of a cytotoxic T lymphocyte antigen-4 (CTLA-4) signaling peptide (dNP2-ctCTLA-4) in Th17, Tc17, γδ T cells, Treg cells in vitro and a mouse model of psoriasis." (PMID 37818377, 2023). "In contrast, CTLA-4-Ig, which employs the extracellular domain of CTLA-4, displayed a propensity to reduce Treg cell populations in vitro and provided ineffective in inhibiting psoriasis progression." (PMID 37818377, 2023). "While CTLA-4-Ig is used in patients with psoriatic arthritis, it only had a moderate impact on psoriasis symptoms." (PMID 37818377, 2023). "We compared dNP2-ctCTLA-4 with CTLA-4-Ig and found that only dNP2-ctCTLA-4 ameliorated the psoriasis progression, with increased Treg cells and inhibited IL-17 production from γδ T cells." (PMID 37818377, 2023). "A previous study from our laboratory found five SNPs (rs11209026 in IL23R, rs10782001 in FBXL19, rs3087243 in CTLA4, rs651630 in SLC12A8, and rs1800453 in TAP1) associated with anti-TNF-induced paradoxical psoriasis reactions." (PMID 36143237, 2022). "CTLA4 blockade has also been reported to increase epidermal thickness and infiltrating T cell counts in mice with psoriasis." (PMID 35154081, 2021). "Few proposed: IL23R (an allele that is protective concerning classical psoriasis), and FBXL19, CTLA4, SCL12A8, TAPl which have an unclear role in paradoxical psoriasis and the outcome of the allele is undetermined." (PMID 30555460, 2018). "In contrast, those with severe psoriasis (BSA > 10%) and PsA may require biologic therapy, including TNFi, IL-17i, IL-23i, or cytotoxic T-lymphocyte-associated-antigen-4-Ig (CTLA4-Ig) agents." (PMID 40004842, 2025). "Remarkably, our data demonstrated a specific impairment in the differentiation of Tc17 cells within the epidermis of Lztr1-deficient mice, accompanied by decreased expression of T activation-related proteins in psoriasis, such as CTLA-4, PD-1, IL22 and TNF-α 12,38,39." (PMID 41162356, 2025). "However, membrane CTLA-4 expression in the skin was higher in moderate forms of psoriasis compared to severe forms." (PMID 38399624, 2024).
psoriasis (continued). "A study utilized spatial transcriptomics to compare the expression of inhibitory T cell ICs, specifically CTLA-4, TIGIT, LAG-3, and PDCD1 (encoding PD-1), on tissue-resident memory T cells in patients with dermatomyositis (Th1-driven) and psoriasis (Th17-driven)." (PMID 38817600, 2024). "Considering the distinct domains of CTLA-4 targeted by these two agents, we hypothesized that they would exhibit different mechanisms of action in treating psoriasis." (PMID 37818377, 2023). "Other psoriasis-linked genes include APOE, CTLA4, DEFB4, GBP6, LCE, MCP1, VDR, and ZNF313." (PMID 37569685, 2023). "Psoriasis, atopic dermatitis and vitiligo have been observed in in 21-56% of CTLA4+/- patients." (PMID 35154081, 2021). "Other genes associated with psoriasis include signal transducer and activator of transcription 4 (STAT4), apoliprotein E (APOE), vitamin D receptor (VDR), and cytotoxic T lymphocyte-associated protein 4 (CTLA4)." (PMID 24069534, 2013). "Abatacept, a human CTLA-4 Ig that inhibits CD28 signaling, was previously shown to ameliorate human psoriasis." (PMID 38226171, 2024). "The role of co-signaling molecules in psoriasis is recognized, mainly including the co-stimulatory molecules CD28, CD40, OX40, CD27, DR3, LFA-1, and LFA-3 and the co-inhibitory molecules CTLA-4, PD-1, and TIM-3." (PMID 34354596, 2021). "It was concluded that CD28/CD80 is crucial in promoting T cell inflammation in psoriasis and the effect of blocking CD28/CD80 signalling by CTLA-4 analogues or by anti-CD28 blocking antibodies is effective against PsA." (PMID 24676037, 2014). "CTLA-4-Ig did not effectively inhibit psoriatic skin inflammation, while the dNP2-ctCTLA-4 peptide significantly reduced psoriasis symptoms and PASI score." (PMID 37818377, 2023). "Moreover, we observed higher CTLA-4 and TIGIT expression by Foxp3int Tregs of PsA patients as compared to psoriasis patients (CTLA-4 + Tregs: 2.3% vs. 3.3%, P= 0.040)(TIGIT + Tregs: 63.2% vs. 69.1%, P = 0.017)." (PMID 36450783, 2022). "The level of CTLA4, a traditional immune checkpoint molecule that inhibits T cell CD28(B7-1) costimulatory function, was reported to be negatively correlated with the severity of psoriasis." (PMID 34768720, 2021). "Soluble CTLA-4 did not correlate with the severity of psoriasis." (PMID 38399624, 2024). "Clinically, CTLA-4-Ig has not been successful in treating psoriasis." (PMID 37818377, 2023). "For example, the CTLA4 signaling in cytotoxic T pathway genes in the turquoise module were expressed robustly in healthy skin but appeared reduced in both lesional and non-lesional skin in AD and psoriasis." (PMID 37809101, 2023). "Moreover, it has been reported that CTLA-4-Ig failed to prevent psoriasis relapse after discontinuation of Ustekinumab treatment." (PMID 37818377, 2023). "In a mouse model of psoriasis (K5.hTGF-b1 transgenic mice), 4-week PUVA treatment suppressed the IL-23/Th17 pathway while augmenting the frequencies of Th2 and IL-10 secreting Foxp3 + Treg, in a CTLA-4 dependent manner, and the levels of many inflammatory cytokines were reduced." (PMID 31533744, 2019). "For instance, CTLA4 expression was significantly increased 21.6-fold in the DPCP day 3 transcriptome, but non-significantly increased 3.7-fold in the psoriasis transcriptome." (PMID 26236467, 2015).
head and neck cancer (43 papers, 2016 to 2026). A primary or metastatic malignant neoplasm affecting the head and neck. "Programmed death ligand 1 and cytotoxic T lymphocyte associated protein 4 present in the exosomes from head and neck cancer cells." (PMID 38059133, 2023). "All the included studies were case-control study evaluating the association of CTLA-4 genetic polymorphisms with the susceptibility to head and neck cancer." (PMID 33327297, 2020). "Previous published studies have reported the association of cytotoxic T lymphocyte antigen 4 (CTLA-4) genetic polymorphisms with the susceptibility to head and neck cancer, but the results remain controversial." (PMID 33327297, 2020). "Accordingly, this systematic review will evaluate the association of CTLA-4 genetic polymorphisms with the susceptibility to head and neck cancer." (PMID 33327297, 2020). "This protocol study will assess the relationship between CTLA-4 genetic polymorphisms and head and neck cancer susceptibility." (PMID 33327297, 2020). "Although previous published studies have reported that the association of CTLA-4 genetic polymorphisms with the susceptibility to head and neck cancer, but the results are still controversial." (PMID 33327297, 2020). "We therefore will conduct a meta-analysis to investigate the relationship between CTLA-4 genetic polymorphisms and head and neck cancer susceptibility." (PMID 33327297, 2020). "In addition, no systematic review has been performed to evaluate the association of CTLA-4 genetic polymorphisms with the susceptibility to head and neck cancer." (PMID 33327297, 2020). "Statistical analyses were utilized using STATA 12.0 and RevMan 5.3, and the odds ratios (ORs) with 95% confidence intervals (95% CI) were used to estimate the strength of the association of CTLA-4 genetic polymorphisms with the susceptibility to head and neck cancer." (PMID 33327297, 2020). "The anti-PD-1/PD-L1/CTLA-4 combination immunotherapy is intended to exert an enhanced re-educating effect in head-and-neck cancers, as it simultaneously targets several routes of T cell suppression." (PMID 36143308, 2022). "A recent study in patients with head and neck cancer, for example, showed that PD-1 and CTLA-4 expression on peripheral T cells increased following radiation therapy." (PMID 34084750, 2021). "In Cetuximab-treated head and neck cancer patients, CTLA-4-positive Tregs correlate with poor prognosis and suppression of NK cell cytotoxicity." (PMID 32640575, 2020). "Analysis of the head and neck cancer TCGA cohort revealed high CTLA-4 and MDSC-related chemokine and an MDSC-rich gene expression profile with a T-cell inflamed phenotype in > 60% of patients." (PMID 28915554, 2017). "Ongoing clinical trials are targeting CTLA4 in Head and Neck Cancer (NCT04290546 and NCT03690986)." (PMID 40246812, 2025). "However, efficacy results vary for the combination of anti-CTLA-4 and anti-PD-L1 in head and neck cancer." (PMID 33921668, 2021). "HPV induces the expression of CTLA-4 on epithelial cells through its E7 oncoprotein, and in the context of HPV-related head and neck cancers, CTLA-4 expression is significantly elevated on TILs, which contributes to an immunosuppressive TME." (PMID 40282436, 2025). "For instance, a combination therapy of CTLA-4 inhibitor (Ipilimumab), CIML NK cell infusion, and interleukin-15 superagonist (N-803) is currently being evaluated for the treatment of advanced head and neck cancer (Clinical trials." (PMID 36932395, 2023). "Similarly, CTLA-4+ and CTLA-4− Tregs from head and neck cancer patients were compared in very small number of samples." (PMID 32041340, 2020). "However, the combination of PD-1 and KIR blockade, or CTLA-4 and KIR blockade, has shown increased response in chemotreated advanced head and neck cancer patients (NCT01714739)." (PMID 32640575, 2020).
head and neck cancer (continued). "The dual checkpoint blockade of PD-1/PD-L1 and CTLA-4 in advanced head and neck cancer patients and low or no PD-L1 tumour cell expression is currently being investigated in different studies, e.g., CheckMate-651 (NCT02741570), CONDOR (NCT02319044), EAGLE (NCT02369874) and KESTREL (NCT02551159)." (PMID 36980527, 2023).
vitiligo (41 papers, 2010 to 2026). Generalized well circumscribed patches of leukoderma that are generally distributed over symmetric body locations and is due to autoimmune destruction of melanocytes. "ICI-induced vitiligo exhibits significant heterogeneity in risk across treatment strategies, with combination therapy and anti-cytotoxic T-lymphocyte-associated protein 4 strategies conferring higher relative risks." (PMID 42299605, 2026). "Polymorphisms in CTLA4 have been identified in vitiligo patients although their association with susceptibility is controversial." (PMID 38720888, 2024). "ICI monotherapy, PD-1 inhibitors, or CTLA-4 inhibitors also had very significant associations with vitiligo, with RORs of 32.43 (26.85–39.18) and 29.23 (19.48–43.86), respectively." (PMID 37332342, 2023). "Further, low expression of CTLA-4 (cytotoxic T lymphocyte antigen-4) in T cells was also associated with higher vitiligo disease susceptibility." (PMID 35360245, 2022). "We evaluated the association between vitiligo and the CTLA4 +49A/G (rs231775) and CT60 (rs3087243) gene variants in a Mexican population." (PMID 36163113, 2022). "Studies have evaluated the association between CTLA-4 + 49A/G polymorphism and PsO or vitiligo, but the results are inconsistent." (PMID 34899832, 2021). "The adapted treatment algorithm for advanced care providers and nurses features severity assessments and interventions for maculopapular rash, pruritus, and vitiligo caused by anti–PD-1 and CTLA-4 inhibitors." (PMID 29900022, 2017). "The frequency of CTLA-4 gene A49G polymorphism was compared in 175 vitiligo patients with 180 age/ethnicity and sex matched controls." (PMID 20418973, 2010). "We investigated the possible association between CTLA-4 gene polymorphism in exon 1 (A49G) and vitiligo in patients from South India and compared the distribution of this polymorphism to matched control groups." (PMID 20418973, 2010). "Consistent with previous studies, both meta-analysis and FAERS analysis showed that anti-CTLA-4 combined with anti-PD/L-1 exhibited a much higher risk than monotherapy for most cutaneous adverse events, such as vitiligo, maculopapular rash, and erythema multiforme." (PMID 37332342, 2023). "Additionally, microsatellite polymorphisms in the CTLA-4 gene, encoding the CTLA-4 immune checkpoint molecule, have been demonstrated in European-derived vitiligo patients." (PMID 33240267, 2020). "A total of 116 vitiligo patients and 117 control subjects from northeast Mexico were included in the study and analyzed through PCR-RFLP to determine whether there is an association between vitiligo and CTLA4 +49A/G (rs231775) and CT60 (rs3087243) gene variants." (PMID 36163113, 2022). "Taking the incidence of vitiligo, for example, the CTLA-4 inhibitor ipilimumab has a stronger positive signal than PD-1 inhibitors." (PMID 41552828, 2025). "A full month prior to vitiligo onset in GF-pulps of Smyth chickens, increases in the expression of the inhibitory receptor CTLA4 were observed." (PMID 38720888, 2024). "Vitiligo is another relatively frequent irAE, with an incidence of approximately 11% and 25% with CTLA-4 & PD-1/PDL1 inhibitors, respectively." (PMID 37370736, 2023). "For vitiligo, anti-PD-1/L1 combined with anti-CTLA-4 therapy showed the strongest signal (ROR: 55.89; 95% CI: 42.34–73.78; IC025: 4.73)." (PMID 37332342, 2023). "Consistent with the previous literature, our analysis also found that patients receiving anti-CTLA-4 monotherapy were less likely to develop the selected cutaneous adverse events compared to PD-1 monotherapy, such as vitiligo, PPE, and SJS/TEN." (PMID 37332342, 2023). "In the available data, all ICI-related regimens had significant vitiligo signals, and anti-PD-1/L1 combined with anti-CTLA-4 therapy showed the strongest signal (ROR: 55.89; 95% CI: 42.34–73.78; IC025: 4.73)." (PMID 37332342, 2023).
vitiligo (continued). "For example, vitiligo showed the strongest signal in anti-PD-1/L1 combined with anti-CTLA-4 therapy, and PPE was reported to have the most significant association with anti-PD-1/L1 combined with VEGF(R)-TKIs." (PMID 37332342, 2023). "Genome-wide association studies (GWAS) have identified more than 50 genetic risk variants for vitiligo, including genes related to cytolysis (GZMB, CTLA4, FOXP3) and melanocyte function (TYR, MC1R, XBP1)." (PMID 36182982, 2022). "Along with HLA class II, CTLA4 and PTPN22 are likely two of the genes that underlie the epidemiologic association of vitiligo with other autoimmune diseases in European-derived whites." (PMID 35884944, 2022). "Blocking cutaneous lymphocyte antigen-4 (CTLA-4) and program cell death protein 1 (PD-1) for melanoma treatment induce and exacerbate vitiligo, presumably by removing negative regulation that prevents autoimmune activation of these cells." (PMID 33737930, 2021). "Decreased CTLA-4 mRNA expression has been reported in whole blood of vitiligo patients, and PD-1 expression on CD8+ T cells is positively correlated with disease activity, suggesting increasing activation." (PMID 33737930, 2021). "The authors noted the pathogenesis of CTLA-4–induced vitiligo is not well understood, and further investigation is needed." (PMID 29900022, 2017). "For example, irradiated B16 tumor cells producing GM-CSF (GVAX) combined with a blocking monoclonal antibody to CTLA-4 breaks tolerance to melanocyte differentation antigens, resulting in protective anti-tumor immunity and vitiligo." (PMID 21911918, 2011). "Besides, the patients who exhibit variations in CTLA4 or NLRP1, which regulates inflammasome activity, can be identified early as having an increased risk of developing vitiligo." (PMID 40837363, 2025). "In patients with vitiligo, the levels of soluble CTLA4 and full-length CTLA4 mRNA are decreased." (PMID 40136446, 2025). "Therefore, the CTLA-4 inhibitor ipilimumab exhibits an extremely strong signal for vitiligo (ROR value = 45.53), significantly higher than that of nivolumab and pembrolizumab." (PMID 41552828, 2025). "The incidence of vitiligo, as estimated by the fixed-effect model, was highest for the IO combination (10.1%) and PD-1 monotherapy (7.9%), followed by the IO + chemotherapy (3.7%), CTLA-4 monotherapy (3.2%), and PD-L1 monotherapy (0.54%) groups (p < 0.001)." (PMID 38254829, 2024). "Examination of growing feathers from vitiligo-susceptible Brown line chickens revealed anti-inflammatory immune activities which may be responsible for preventing vitiligo (IL10, CTLA4, FOXP3)." (PMID 38720888, 2024). "We investigated whether the CTLA4 +49A/G (rs231775) and CT60 (rs3087243) gene variants are associated with vitiligo in a sample of Mexican patients and healthy control subjects." (PMID 36163113, 2022). "Maculopapular eruption, pruritus, and SJS/TEN are more commonly seen with anti-CTLA-4 blockades, whereas lichenoid dermatitis, psoriasiform dermatitis, vitiligo-like depigmentation, and bullous pemphigoid more frequently occur in patients treated with anti-PD-1/PD-L1 blockades." (PMID 35448208, 2022). "In conclusion, the CTLA4 gene variants rs231775 and rs3087243 do not constitute a risk factor in the development of vitiligo in the analyzed northeastern Mexican population." (PMID 36163113, 2022). "Among the irAEs encountered in ICI-treated patients, a systematic review has documented that all-grades colitis, hypophysitis, and rash were more frequent with anti-CTLA-4 agents, whereas pneumonitis, hypothyroidism, arthralgia, and vitiligo were more common with anti-PD-1 blockades." (PMID 35448208, 2022). "The overall analysis and subgroup analysis based on race, genotype frequency, and heterogeneity failed to prove the association between CTLA-4 + 49A/G polymorphism and vitiligo." (PMID 34899832, 2021).